NME1 (NME/NM23 nucleoside diphosphate kinase 1)
Diseases named in the same sentence as NME1 in open-access papers (continued):
Sharing a sentence is not in itself a finding about the gene and the disease.
melanoma (continued). "Herein, we systematically examined the contribution of NME1 to total NHEJ, A-NHEJ and HR pathways of DSBR in melanoma cells." (PMID 32824412, 2020). "To address this, we screened protein expression of five melanoma metastasis suppressors (BRMS1, gelsolin, GAS1, NME1/NM23-H1, and KAI1) following KDELR3 knockdown." (PMID 31949145, 2020). "Having recently observed that spheroids derived from melanoma cell lines exhibit cellular heterogeneity in expression of the metastasis suppressor NME117, we investigated the expression pattern of NME1 under monolayer culture conditions." (PMID 32029850, 2020). "NME/NM23 nucleoside diphosphate kinase 1 (NM23), also known as NME1, is first reported as an antitumor–metastasis gene that was correlated with metastasis in murine melanoma." (PMID 30662464, 2018). "It is important to note that NME1 expression in vitro did not affect the proliferation of melanoma cell lines." (PMID 39063217, 2024). "The first metastasis suppressor, NME/Nm23 nucleoside diphosphate kinase (NDPK) 1 (NME1), was identified in 1988 by comparing the differentially expressed genes in high- and low-metastatic murine melanoma cell lines." (PMID 37970212, 2023). "The first metastasis suppressor gene identified was the mouse homologue of NME1, which was absent in metastatic, but present in non-metastatic mouse melanoma cell lines." (PMID 36010906, 2022). "In addition, the PI3K/AKT signaling pathway was shown to be regulated by NME1 and NME2 metastasis suppressors in the WM793B primary melanoma cell line." (PMID 36077308, 2022). "In a prior study, we observed that expression of NME1 was required for maintenance of a stem-like phenotype in melanoma cells cultured under non-adherent conditions that promote spheroid growth." (PMID 32029850, 2020). "Non-metastatic cells 1 (NME1), also known as NM23-H1, was the first metastasis suppressor discovered by its reduced mRNA transcript levels in a murine melanoma cell line exhibiting high metastatic activity." (PMID 32977620, 2020). "Taken together, these observations indicated that expression of the NME1-EGFP fusion protein recapitulated the heterogeneous expression profile of native NME1, providing a robust approach for acquisition of viable melanoma subpopulations and assessments of their malignant potential." (PMID 32029850, 2020). "Moreover, mice rendered hemizygous-null at the tandemly-arranged NME1 and NME2 loci (herein designated NME1/2+/−) are highly vulnerable to UV-induced melanoma in situ and epidermal inclusion cyst formation on tail skin, consistent with a deficit in DNA repair." (PMID 28788083, 2017). "Consistent with the classical definition of an MSG, the NME1/2+/− genotype did not affect the average growth rate of primary tumors, time of onset of UV-induced melanomas (~180 days), or penetrance of the melanoma phenotype (~70% of irradiated mice)." (PMID 28788083, 2017). "The nm23-H1 gene (NME1), localized on chromosome 17q21.3 was first isolated as a metastasis suppressor gene by differential screening of cDNA library from high and low metastatic clones of a murine melanoma cell line." (PMID 19171060, 2009). "In addition, we have observed coordinate downregulation of NME1 and NME2 in human melanoma cell lines of metastatic origin, and this has been reported in human cervical carcinoma specimens as well, suggesting cooperative impacts of NME1 and NME2 on metastatic activity." (PMID 33024267, 2021). "The NME1 (initially designated nm23, for Negative in Metastasis clone 23”) gene was identified by virtue of reduced expression of its cognate transcript in a metastatic clone of the mouse melanoma cell line K-1735." (PMID 28788083, 2017). "While UV-induced melanomas of the HGF/SF strain failed to exhibit metastasis to lymph nodes or distal organs, robust metastatic activity was seen in HGF/SF × NME1/2+/− hybrids bearing large (500 mm3) melanomas on back skin." (PMID 28788083, 2017).
melanoma (continued). "In summary, the ability of NME1 to directly regulate multiple DSBR pathways represents a novel molecular mechanism likely to impact metastatic potential and resistance to therapy in advanced melanoma and possibly other cancers as well." (PMID 32824412, 2020). "Moreover, the HGF/SF model system revealed prototypical MSG activity for NME1 and/or NME2 for the first time in an in vivo setting of melanoma, with suppression of metastasis in the absence of an effect on primary tumor growth." (PMID 28788083, 2017).
neuroblastoma (36 papers, 1993 to 2024). Neuroblastoma (NB) is the most common solid, extracranial childhood tumor. "Neuroblastoma is a pediatric cancer associated with aggressive cases with focal amplification on the arm of chromosome 17q of a region that includes NME1 and NME2 located at 17q23." (PMID 39063217, 2024). "Of the remaining two genes, NME1 has been described for its prognostic value in neuroblastoma and mutations in NME1 correlate with an aggressive phenotype." (PMID 32211329, 2020). "Instead, higher NME1 expression was significantly associated with poor prognosis in patients with neuroblastoma and osteosarcoma, as well as cervical cancer." (PMID 32795291, 2020). "Expression of NME1 is strongly associated with neuroblastoma patient outcomes, with elevated NME1 expression associated with reduced overall and event-free survival and with the strongest associations of any of the NME family member genes." (PMID 32392889, 2020). "In conclusion, our study further delineates the associations of NME1 expression with chromosome 17q amplification, tumor prognostic features, and overall patient outcomes in neuroblastoma." (PMID 32392889, 2020). "We have also demonstrated associations between NME1 expression and neuroblastoma cell migration and differentiation." (PMID 32392889, 2020). "The S120G mutation in NME1 has been found in several aggressive pediatric neuroblastomas." (PMID 39063217, 2024). "In 21% of neuroblastoma cases, NME1 Ser120 is mutated to a glycine." (PMID 39063217, 2024). "However, in prostate and ovarian cancer, neuroblastoma or haematological malignancies, high NME1 expression is the hallmark of bad prognosis." (PMID 36010906, 2022). "The S120G mutation in NME1 has also been studied since it was found in neuroblastoma." (PMID 32823988, 2020). "The observed associations between specific NME1 overexpression with other markers of poor patient prognosis such as MYCN amplification reinforces our suggestion that histidine-dependent signaling is likely to be involved in neuroblastoma pathogenesis." (PMID 32392889, 2020). "Additional cluster analyses identified enrichment for pathways related to focal adhesions among the candidate NME1 target proteins, consistent with our observed association of NME1 expression with neuroblastoma cell migration, as well as possible involvement in protein translation and glycolysis." (PMID 32392889, 2020). "Mutations in NME1 have been identified in aggressive neuroblastomas." (PMID 26269723, 2014). "It has also been demonstrated that NME1/2 plays a role as a metastasis promoter in neuroblastoma and lymphoma." (PMID 39063217, 2024). "Due to the genetic landscape of neuroblastoma, it can be postulated that the pro-metastatic role of NME1 is due to an amplification of NME1 expression." (PMID 39063217, 2024). "Expression of NME1 or NME1-S120G in neuroblastoma cells promotes migration and invasion in culture and metastasis in vivo." (PMID 39063217, 2024). "Next to IGF2BP1, this analysis unraveled top-ranking of BIRC5 and TOP2A among common essential as well as NME1 among neuroblastoma essential Chr 17q genes." (PMID 37246217, 2023). "Many of these, e.g. NME1, PYCR1, TK1, BIRC5 and TOP2A, are located on Chr 17q, are upregulated in unfavorable neuroblastoma and associated with poor patient outcome." (PMID 37246217, 2023). "Our results, in each of these three steps of validation, confirm the prognostic capability of AHCY, DPYLS3, and NME1, and highlight their key role in neuroblastoma prognosis." (PMID 36870971, 2023). "It has been demonstrated that NME1-S120G is more effective in promoting cell invasiveness and metastasis of neuroblastoma in vitro and in vivo." (PMID 36870971, 2023). "Our results pointed out the relevant impact of the genes AHCY, DPYSL3 and NME1 on neuroblastoma prognosis as future targets for future neuroblastoma genetics studies and the development of novel therapies." (PMID 36870971, 2023).
neuroblastoma (continued). "In the following text, we report a description of the relevant role of AHCY, DPYSL3, and NME1 in neuroblastoma development highlighted by the studies considered by the state-of-the-art literature, as described in subsection Validation on the literature." (PMID 36870971, 2023). "The NME1 gene is located in the 17q21.3 region, whose gain is a common evaluated factor predicting adverse clinical outcome in neuroblastoma patients." (PMID 36870971, 2023). "NME1 play a potential role to regulated neuroblastoma or hepatocellular carcinoma pathogenesis and NME2 can inhibit gastric cancer metastasis." (PMID 34748517, 2021). "This work demonstrates the presence of phosphorylated histidine in neuroblastoma cells and tumors and explores the specific roles of NME1 expression in neuroblastoma pathogenesis." (PMID 32392889, 2020). "The NME1 gene is located within the chromosome 17q21 region commonly amplified in neuroblastoma tumors, and NME1 expression is highest in tumors with chromosome 17q amplification, suggesting a potential oncogenic role." (PMID 32392889, 2020). "The cellular functions directly regulated by NME1 expression and histidine kinase activity in neuroblastoma remain to be determined." (PMID 32392889, 2020). "NME1, NME2, and NME3 were also each identified from the NME1 immunoprecipitated from neuroblastoma cells, which also supports the notion of hetero-oligomerization and the autophosphorylation of these family members." (PMID 32392889, 2020). "The NME1 gene is located in the 17q21.3 region, and high NME1 expression is correlated with poor neuroblastoma patient outcomes." (PMID 32392889, 2020). "The gene for NME1 (also known as NM23, NDPK-A) is located in the chromosome 17q21 region commonly amplified in neuroblastoma tumors, suggesting a potential oncogenic role in neuroblastoma pathogenesis." (PMID 32392889, 2020). "Our data demonstrating phenotypic effects of isolated NME1 depletion in neuroblastoma cell lines, however, suggests some unique functional roles of NME1." (PMID 32392889, 2020). "In order to confirm the presence of NME1 and of histidine phosphorylation in human neuroblastoma tumors, we analyzed mouse orthotopic xenograft tumors by immunoblot." (PMID 32392889, 2020). "NME1 depletion resulted in significantly reduced neuroblastoma cell differentiation in response to 13-cis-retinoic acid." (PMID 32392889, 2020). "In contrast, in hematological malignancies and other types of cancer, such as ovarian, prostate, and neuroblastoma, higher expression of NME1 is correlated with a bad prognostic." (PMID 32823988, 2020). "At least two genes, survivin/BIRC5 and nm23/NME1, mapping to 17q gain regions, have been implicated contributing to the aggressive phenotype of neuroblastomas." (PMID 28055978, 2017). "Specifically, copy number variations in the central neuroblastoma genes NME1 and ALK, both of which are found to be mutated in neuroblastoma as well support this reasoning." (PMID 25528190, 2014). "The abundance of this protein is reduced in some tumor cells of high metastatic potential but increased NME1 levels have been correlated with aggressive tumor features in neuroblastoma." (PMID 23717685, 2013). "Correlation between MYCN overexpression and upregulation of NME1 expression has been reported both in NBTs and neuroblastoma cell lines." (PMID 18700951, 2008). "Furthermore, in the same paper, the presence of histidine phosphorylation in neuroblastoma cells and tumors was detected on a number of proteins, including NME1 and NME2." (PMID 39063217, 2024). "On the other hand, NME1 expression correlates with aggressive neuroblastoma tumor features." (PMID 39063217, 2024). "The prognostic role of AHCY, DPYSL3, and NME1 The evaluation of the impact of AHCY, DPYSL3 and NME1 on the prognosis of patients affected by Neuroblastoma showed the importance of these genes in terms of association with the death rate and prediction of the survival probabilities across time." (PMID 36870971, 2023).
neuroblastoma (continued). "However, the molecular mechanism(s) by which NME1 promotes neuroblastoma metastasis still remains elusive." (PMID 36870971, 2023). "In contrast, in pediatric cancer such as neuroblastoma, it correlates with aggressive neuroblastoma tumor features while increased NME1 expression has been identified as a component of gene expression, signatures most significantly associated with poor neuroblastoma patient outcomes." (PMID 36870971, 2023). "Indeed, NME1 shRNA knock-down disrupts differentiation of neuroblastoma cells induced by 13-cis-retinoic acid (CRA) treatment." (PMID 36870971, 2023). "However, in other tumors, upregulated NME1 levels have been correlated with poor prognosis, especially in neuroblastoma and some forms of leukemia and lymphoma." (PMID 33917317, 2021). "Our results clearly require further validation, and future studies will need to further evaluate the functional role of NME1 histidine kinase activity in neuroblastoma pathogenesis, including its potential roles in cell migration, metastasis, and differentiation." (PMID 32392889, 2020). "Our studies have further identified a potential role for NME1 in neuroblastoma cell migration and differentiation, as demonstrated by the fact that NME1-depleted neuroblastoma cells exhibited more rapid migration into scratch wounds and reduced CRA-induced differentiation." (PMID 32392889, 2020). "Increased NME1 gene copy number has been directly identified in 14%–23% of neuroblastoma tumors, and increased NME1 expression has also been identified in high-risk neuroblastoma tumors, possibly secondary to MYCN-mediated regulation of NME1 expression." (PMID 32392889, 2020). "In contrast to these adult tumors, elevated NME1 expression correlates with aggressive neuroblastoma tumor features while increased NME1 expression has been identified as a component of gene expression, signatures most significantly associated with poor neuroblastoma patient outcomes." (PMID 32392889, 2020). "NME1 expression is also higher in tumors with MYCN oncogene amplification and in tumors from patients with stage 4 disease, consistent with its association with more aggressive neuroblastoma tumors." (PMID 32392889, 2020). "Compared to control, stable transfectants of human neuroblastoma NB69 cell lines expressing Nme1 and mutant Nme1S120G form 2.8 and 3.6 times more colonies on soft agar, respectively, indicating that Nme1 aberrations provide neuroblastoma cells with additional in vitro colonization ability." (PMID 31877804, 2019). "Interestingly, silencing NME1 in neuroblastoma increases cell migration." (PMID 39063217, 2024). "However, the functional roles and signaling activity of NME1 in neuroblastoma cells and tumors are unknown." (PMID 32392889, 2020). "The relative roles of NME1 and NME2 in these hexamers, in the regulation of histidine phosphorylation, and in neuroblastoma pathogenesis remain undefined." (PMID 32392889, 2020). "We have identified the presence of histidine phosphorylation of a number of proteins, including NME1 and NME2, in neuroblastoma cells and tumors, and have identified potential links between NME1 expression and neuroblastoma cell migration and differentiation." (PMID 32392889, 2020). "Products of the NME1 and NME2 genes have been suggested to be the downstream of the c-myc regulatory pathway and involved in the down-regulation of cdc42 function in neuroblastoma." (PMID 25700270, 2015). "Additionally, as retinoic acid exerts its differentiation-stimulating effects through ROR2 and RORa in cultured mouse hippocampal neurons and neuroblastoma cell lines, we examined the roles of both RORa and ROR2 receptors in NME1-promoted neurite growth." (PMID 34623600, 2022). "Determination of the functional role of NME1 in neuroblastoma pathogenesis has been limited by the lack of reagents available to evaluate the role of histidine phosphorylation and histidine kinase activity." (PMID 32392889, 2020).
neuroblastoma (continued). "However, the inverse correlations of NME1 and the recently identified histidine phosphatase LHPP with neuroblastoma patient outcomes suggests a significant role for the regulation of histidine phosphorylation in neuroblastoma pathogenesis." (PMID 32392889, 2020). "However, the functional roles of NME1 in pediatric cancer in general and in neuroblastoma pathogenesis in particular have not been defined." (PMID 32392889, 2020). "Thus, the detection of serum NME1 protein levels, contributing to predictions of clinical outcome in patients with neuroblastoma, may be also proposed as not invasive prognostic markers." (PMID 36870971, 2023). "However, the functional roles of NME1 in neuroblastoma pathogenesis have not been defined." (PMID 32392889, 2020).
hepatocellular carcinoma (25 papers, 2011 to 2025). A malignant tumor that arises from hepatocytes. "NME1 expression is associated with a bad prognosis and metastasis in renal and bladder cancers, leukemia, hepatocellular carcinoma, squamous cell lung carcinoma, ovarian cancer, and prostate cancer." (PMID 39063217, 2024). "Key cancer-related pathways such as “Gastric cancer”, “Hepatocellular carcinoma” and “Proteoglycans in cancer” were prominently identified in network, bar and bubble plots, and genes such as NME1, PSAT1, AHCY and PIGR were significantly involved." (PMID 40567612, 2025). "When NME1 is depleted in hepatocellular carcinoma (HCC), MAPK activity is increased through hyperactivation of ERK." (PMID 39063217, 2024). "Second, the incidence of lung metastases increased significantly in NME1 knockout mice prone to develop hepatocellular carcinoma." (PMID 37353690, 2023). "Consistent with a role for NME1 in endocytosis of MT1-MMP, in human hepatoma and colorectal tumor cell lines in which NME1 is silenced, expression of a mutant MT1-MMP deleted of its catalytic domain inhibits invasion." (PMID 37353690, 2023). "After silencing NME1 expression in human hepatoma and colon carcinoma cells, cellular scattering, motility, and extracellular matrix invasion were all promoted." (PMID 27518571, 2016). "Moreover, in non-invasive hepatoma and colon tumor epithelial cell lines, silencing NME1 reduces the amount of E-cadherin on the cell surface, correlating with reduced cell–cell adhesion." (PMID 37353690, 2023). "Consistent with this, NME1 is downregulated or absent at the invasive front of clinical samples of hepatocellular carcinoma and colon cancers whereas it is robustly present in the center of the tumors." (PMID 37353690, 2023). "Supporting our conclusion, NME1 is also reduced or absent at the invasive front of human hepatocellular carcinoma and colon cancers, as compared to its strong expression in the tumor central area." (PMID 34012098, 2021).